IFT88 (intraflagellar transport 88)
Description:
Positively regulates primary cilium biogenesis. Also involved in autophagy since it is required for trafficking of ATG16L and the expansion of the autophagic compartment.
Synonyms: TG737; TTC10; hTg737; D13S1056E; MGC26259; DAF19
Tractability: PROTAC: ubiquitination databases record sites on it.
Gene: Protein-coding gene on chromosome 13 (20,566,600 to 20,691,697, forward strand). Ensembl gene ENSG00000032742.
Subcellular location: Cytoplasm, cytoskeleton, microtubule organizing center, centrosome, centriole; Cell projection, cilium; Cytoplasm, cytoskeleton, cilium basal body; Cytoplasm, cytoskeleton, microtubule organizing center, centrosome; Cytoplasm; Cell projection, cilium, flagellum; Cytoplasm, cytoskeleton
Subcellular location (Human Protein Atlas): End piece; Microtubules; Primary cilium; Basal body; Centriolar satellite; Connecting piece; Cytokinetic bridge; Mid piece; Mitotic spindle; Principal piece
Pathways (Reactome):
Autophagy: Aggrephagy; Chaperone Mediated Autophagy; Late endosomal microautophagy
Organelle biogenesis and maintenance: Intraflagellar transport
Signal Transduction: Hedgehog 'off' state
Gene Ontology:
Molecular function: protein binding; kinesin binding
Biological process: positive regulation of cilium assembly; cilium assembly; inner ear receptor cell stereocilium organization; intraciliary anterograde transport; intraciliary transport; kidney development; non-motile cilium assembly; regulation of autophagosome assembly; regulation of cilium assembly; response to silicon dioxide
Cellular component: centriole; centrosome; ciliary basal body; cilium; intraciliary transport particle A; intraciliary transport particle B; ciliary base; ciliary tip; cytoplasm; cytosol; manchette; motile cilium; non-motile cilium; sperm flagellum; sperm head-tail coupling apparatus; cytoskeleton; intraciliary transport particle
Genetic constraint (gnomAD): Loss-of-function variants: 6 observed, 11.57 expected, observed/expected ratio (o/e) 0.52, 90% interval 0.28 to 1.02. The upper end of that interval is the gene's LOEUF score, 1.02, which puts it in group 4 of 6, group 1 being the genes least tolerant of losing a copy. Missense variants: 138 observed, 147.21 expected, observed/expected ratio (o/e) 0.94, 90% interval 0.81 to 1.08. Synonymous variants: 42 observed, 48.4 expected, observed/expected ratio (o/e) 0.87, 90% interval 0.68 to 1.12.
Homologues: Orthologues: chimpanzee IFT88 (99% identical), macaque IFT88 (96% identical), dog IFT88 (91% identical), rabbit IFT88 (90% identical), guinea pig IFT88 (90% identical), mouse Ift88 (89% identical), rat Ift88 (89% identical), pig IFT88 (86% identical), tropical clawed frog ift88 (79% identical), zebrafish ift88 (75% identical), Caenorhabditis elegans osm-5 (45% identical). Paralogues in human: TMTC1 (13% identical), TTC7A (13% identical), TTC7B (13% identical), TMTC2 (12% identical), TMTC4 (11% identical), CFAP70 (11% identical), TMTC3 (11% identical), TTC6 (11% identical), TTC16 (9% identical), TTC34 (9% identical), BBS4 (9% identical), OGT (9% identical), and 2 more.
Diseases named in the same sentence as IFT88 in open-access papers:
IFT88 is named in the same sentence as 77 diseases in open-access papers, as found by Europe PMC text mining. Sharing a sentence is not in itself a finding about the gene and the disease. The quoted sentences say what the papers report.
ciliopathy (24 papers, 2008 to 2025). A genetic disorder of the cellular cilia or the cilia anchoring structures, the basal bodies, or of ciliary function. "IFT88 is a component of the IFT transport machinery (IFT-B complex) and variants in IFT88 have been identified in individuals with non-syndromic recessive retinal degeneration, as well as in other ciliopathies." (PMID 39934925, 2025). "The past studies indicate that mouse models of ciliopathies caused by Tulp1 and IFT88 mutations manifest rhodopsin mislocalization and accumulation of rhodopsin-laden vesicles, as was observed in this study." (PMID 32376599, 2020). "IFT88 has been implicated as a key contributor to various ciliopathy phenotypes." (PMID 40076734, 2025). "A separate study of patients with non-syndromic cleft lip and cleft palate identified missense mutations in the IFT88 coding sequence, which may represent a partial loss of IFT88 function, ultimately causing a ciliopathy associated with human cleft palate." (PMID 40076734, 2025). "IFT88, a crucial protein for cilium formation, renders the investigation of IFT88 mutant animal models a vital approach to understanding human ciliopathies." (PMID 40076734, 2025). "Ift88 knockout mice thus develop anterior segment dysgenesis, and there is a reported case of human corneal opacification as the result of ciliopathy." (PMID 37239394, 2023). "The loss of IFT88 expression in dermal fibroblasts has been previously reported as a readout for impaired IFT in Jeune and Mainzer-Saldino ciliopathy patients." (PMID 34365092, 2021). "Studies of experimental inflammatory atherosclerosis, which is altered by conditional deletion of Ift88 and thus removal of cilia, and the ciliopathy polycystic kidney disease (PKD) implicate cilia/ciliary proteins in inflammatory components of pathogenesis." (PMID 32503942, 2020). "This high-confidence list includes many established ciliopathy genes such as TTC26, CEP83, IFT88, and SPATA7, as well as 14 of 25 known JS causative genes." (PMID 26026149, 2015). "Individuals with ciliopathies resulting from defects of the primary cilia often have CLP, and tissue-specific deletion of the intraflagellar transport genes intraflagellar transport 88 (Ift88) or kinesin family member 3A (Kif3a) in mice causes CLP." (PMID 30760477, 2019).
polycystic kidney disease (12 papers, 2011 to 2025). A usually autosomal dominant and less frequently autosomal recessive genetic disorder characterized by the presence of numerous cysts in the kidneys leading to end-stage renal failure. "They next discovered IFT88 corresponded to Tg737, a gene mutated in a mouse model for polycystic kidney disease, and pushed on by investigating mouse kidneys with the presence of cilia at the surface of epithelial cells in normal tubules." (PMID 25974046, 2015). "For example, a renal-specific inactivation of Hnf1α in mice has been implicated in polycystic kidney disease and shown to mediate the down-regulation of several cystic disease genes localised to primary cilia, including Ift88 and Ift122." (PMID 23326503, 2013). "To do this we used a chondrocyte cell line (denoted Oak Ridge Polycystic Kidney (ORPK)) harbouring a hypomorphic insertional mutation in TG737 encoding for polaris/IFT88 protein and resulting in reduced ciliation." (PMID 24330727, 2013). "An immortalized cell line, 94D, derived from the corticalcollecting duct cells of an Oak Ridge Polycystic Kidney mutant mouse(orpk), and deficient in IFT88, was generated by Yoder andcolleagues." (PMID 21490950, 2011). "IFT88 was first identified in mammalian cells following an insertional mutation in the non-coding region as part of a random mutagenesis screen, which resulted in a polycystic kidney phenotype (the ‘ORPK’ mouse)." (PMID 32503942, 2020). "The first functional evidence linking primary cilium to cystic disease was derived from Caenorhabditis elegans IFT88 and its mouse homologue, polycystic kidney disease gene tg737 mutant mice." (PMID 36072924, 2022). "At 9 months post DOX, male Ift88 KO mice had polycystic kidneys and elevated BP compared to male controls, while female Ift88 KO mice had very rare renal cysts and reduced BP compared to female controls." (PMID 35274831, 2022). "However, in the renal cells depleted of intraflagellar transport protein IFT88, the first cytokinesis becomes abnormally asymmetric, leading to the formation of multiple lumens and polycystic kidney phenotype in mouse 15,71." (PMID 38065974, 2023). "Indeed, the disruption of IFT88 (intraflagellar transport protein 88 homolog) results in polycystic kidney disease in mice." (PMID 33339422, 2020). "Loss of Ift88 results in the absence of cilia and causes left-right asymmetry defects, disordered Hedgehog signaling, and polycystic kidney disease, all of which are explained by aberrant ciliary function." (PMID 26465598, 2015). "In the oak ridge polycystic kidney (ORPK) mouse model of PKD, ciliary dysfunction is caused by a mutation in a sub-state of IFT88, rather than a deletion of the gene." (PMID 40076734, 2025).
cyst (9 papers, 2017 to 2025). A sac-like closed membranous structure that may be empty or contain fluid or amorphous material. "The cilia-dependent cell fate determination may explain the observation in the mouse that loss of Ift88 prior to P14 results in rapid and widespread cyst formation, whereas loss of Ift88 after P14 results in late-onset and focal cyst formation." (PMID 36533556, 2022). "IFT88 plays a pivotal role in a variety of cilium-related processes, including organ fibrosis and cyst formation, metabolic regulation, chondrocyte development, and neurological functions." (PMID 40076734, 2025). "Similar findings are seen in double knockout models involving Ift88 (also known as Tg737) and Pkd1, supporting the idea that cilia can promote cyst expansion when polycystins signaling is lost." (PMID 40801635, 2025). "Our previous studies demonstrated that renal resident macrophages promote cyst growth in the Ift88 mutant kidney after ischemia/reperfusion injury and their depletion reduces cyst severity." (PMID 36457161, 2023). "Furthermore, inhibition of resident macrophage proliferation using a CSF1 receptor antagonist reduced cyst severity in adult-induced Ift88 mutants following injury." (PMID 36457161, 2023). "Indeed, in mice mutants for IFT88/Tg737, an initially mild multifocal microscopic dilation of kidney tubule was rapidly followed by a marked dilation of the lumen and by cyst formation." (PMID 29203870, 2017). "It has been found that inactivation of Pkd1 or an essential IFT gene, tg737 (IFT88) in adult mice results in no cyst formation until months after deletion of either gene." (PMID 33886508, 2021).
Hydrocephalus (8 papers, 2007 to 2025). Hydrocephalus is an active distension of the ventricular system of the brain resulting from inadequate passage of CSF from its point of production within the cerebral ventricles to its point of absorption into the systemic circulation. "Mutations in IFT88 cause the loss of motile cilia in blood vessels, potentially impairing blood flow and resulting in a pathology similar to obstructive hydrocephalus." (PMID 40076734, 2025). "The pleiotropic phenotype of the Tg737orpk mutant mouse, which lacks the cilia assembly protein IFT-88/Polaris, includes hydrocephalus caused by alterations in the ion transport activity of the ependymal cells and consequent overproduction of CSF." (PMID 17683645, 2007). "Knock-out mice for genes involved in ciliogenesis such as Cadherin EGF LAG Seven-Pass G-Type Receptor 2/3 (Ceslr2/3), Intraflagellar transport 88 (Ift88), and Kinesin family member 6 (Kif6), all presenting ependymal cell cilia dysfunction, also exhibit hydrocephalus." (PMID 36859317, 2023). "Moreover, ablation of the embryonic primary cilia by conditional deletion of Kif3a and Ift88 also disrupts ependymal cilia, resulting in postnatal hydrocephalus." (PMID 28931858, 2017). "Previous studies on the role of Polaris (IFT88) in preventing hydrocephalus showed similar results." (PMID 19774080, 2009).
cystic kidneys (7 papers, 2009 to 2026). "In murine models and humans, Ift88 mutations contribute to renal cysts, epithelial proliferation and impaired immune responses." (PMID 41588821, 2026). "In Ift88 KO mice 9 months post‐induction, males manifested salt‐dependent hypertension associated with prominent cystic kidneys, while females had reduced BP compared to age‐ and sex‐matched controls while fed a high salt diet." (PMID 35274831, 2022). "Although some of the defects, such as cardiac looping, holoprosencephaly, polydactyly, and cystic kidney are common in major ciliary gene mutations, such as Kif3a or Ift88, the phenotypic spectrums of the mouse models for DAP genes are diverse." (PMID 36407107, 2022). "Significantly, Ift88 inactivation partially reduced cell proliferation, suppressed the severity of renal cyst and fibrosis, and improved kidney function in Invs mutants." (PMID 36920028, 2023). "We previously induced nephron specific Ift88 gene KO (Ift88 KO) in mice at 2 months of age; male mice developed PKD 9 months post Ift88 KO (at 11 months of age), while female Ift88 KO mouse kidneys had normal or rare renal cysts at this age." (PMID 35274831, 2022). "Another possible factor is the reduced urinary NO excretion in male Ift88 KO mice cystic kidneys observed during high salt intake." (PMID 35274831, 2022). "This response, when inhibited through an IFT (Tg737/IFT88) mutation, results in the development of cystic kidney." (PMID 22423203, 2009). "Notably, NKCC2, phospho‐NCC, and ENaC‐α expression were all downregulated in male Ift88 KO cystic kidneys raising the possibility of a compensatory response to enhanced NHE3 activity." (PMID 35274831, 2022). "Conditional IFT88 silencing can also lead to cystic kidneys however these mice were shown to remain healthy with no signs of kidney disease two months after treatment and do not have significant kidney deficits or other outwardly apparent phenotypes until nine months after IFT88 deletion." (PMID 39747370, 2025).
Obesity (7 papers, 2016 to 2024). Accumulation of substantial excess body fat. "Cilia on neurons are required for normal energy homeostasis as conditional knockout models of ciliogenesis genes, IFT88 and Kif3A, cause obesity." (PMID 36568981, 2022). "Induced ablation of the kinesin-2 subunit KIF3A or IFT88 throughout the nervous system or in the hypothalamus cause obesity in mice." (PMID 26926121, 2016). "To test whether loss of other cilia-related genes in LRb-containing neurons recapitulate the obesity phenotype induced by ablation of the Bbs1 gene, we crossed the mice bearing the conditional allele of the Ift88 gene with the LRbCre mice." (PMID 26926121, 2016). "Ablation of primary cilium by conditionally knocking out Ift88 in adult mice leads to obesity — either when deleted ubiquitously, specifically in neurons, or only in the PVN — directly implicating PVN cilia in the control of feeding behavior." (PMID 36692018, 2023). "Conditional knockout of IFT88 or Kif3A in neonatal POMC-expressing neurons leads to obesity in adult mice." (PMID 36568981, 2022). "Further, ablation of the complex B genes, Ift88 or Kif3a, either during adulthood or specifically in POMC-expressing cells of mice, causes hyperphagia, obesity and hyperleptinemia." (PMID 27482817, 2016). "A recent study showed that inhibition of ciliogenesis in developing POMC neurons, which was realized by depleting Kif3a or Ift88, led to adulthood obesity in mice; these mice showed disruption of axonal projections through impaired lysosomal protein degradation in POMC neurons." (PMID 34211092, 2021). "The VMH-specific primary cilia KO (IFT88-KOSF-1) mice exhibited metabolic dysregulation linked to decreased sympathetic nervous activity (SNA) and central leptin resistance, which led to marked obesity." (PMID 34211092, 2021). "We further show that loss of BBSome subunits, but not IFT88, impairs the trafficking of the LRb to the plasma membrane leading to leptin resistance independently of cilia and obesity." (PMID 26926121, 2016). "Here we show that inhibition of ciliogenesis in POMC-expressing developing hypothalamic neurons, by depleting ciliogenic genes IFT88 and KIF3A, leads to adulthood obesity in mice." (PMID 33188191, 2020). "Further, deletion of Ift88 in POMC-expressing cells in mice resulted in hyperphagia and obesity, demonstrating that ciliary function specifically of POMC-expressing neurons is crucial to the neuronal circuitry that controls appetite." (PMID 27482817, 2016). "Instead, we demonstrate that silencing BBS proteins, but not IFT88, impair the trafficking of the LRb to the plasma membrane leading to central leptin resistance in a manner independent of obesity." (PMID 26926121, 2016). "Moreover, mechanistic studies demonstrated that the deletion of the expression of BBS proteins, but not Ift88, impaired LepRb trafficking to the plasma membrane, leading to central leptin resistance in a manner independent of obesity." (PMID 34211092, 2021). "The obese phenotype of the IFT88 KOSF-1 mice presented with decreased energy expenditure, which appeared to be a primary consequence of reduced sympathetic outflow rather than a secondary effect of obesity." (PMID 34211092, 2021).
cystic kidney disease (6 papers, 2013 to 2026). A congenital or acquired kidney disorder characterized by the presence of renal cysts. "Around the same time, a mutation in Tg737, now termed Ift88, a gene essential for ciliary function in Chlamydomonas reinhardtii, was found to cause cystic kidney disease in mice." (PMID 41164956, 2025). "The data also suggest that in our previous kidney injury studies, the ability of T cells to accelerate cystic kidney disease is due to their interaction with the Ift88 deficient epithelium or other cells in the microenvironment." (PMID 39562155, 2024). "Cilia proteins KIF3A, IFT88 and IFT20, which are involved in IFT, are required for renal ciliogenesis; inactivation of each is known to cause cystic kidney disease." (PMID 23762375, 2013). "Previous data from our lab indicate that mice lacking Ift88 (CaggCreERT2Ift88f/f) develop cystic kidney disease within 5–6 months post tamoxifen induction." (PMID 39562155, 2024).
breast carcinoma (5 papers, 2019 to 2025). "However, the role for LRRC56 in breast cancer progression and regulation of IFT88 and associated pathways in metastatic progression of breast cancer has not been defined." (PMID 40388100, 2025). "In summary, our results demonstrate that overexpression of LRRC56 promotes breast cancer progression via upregulating IFT88/YAP1-RhoA/ROCKs pathway, reprogramming extracellular matrix, and enhancing epithelial-mesenchymal transition." (PMID 40388100, 2025). "However, the expression of IFT52 and IFT81 was upregulated in the breast cancer cells, and the expression of IFT88 showed an undetectable difference between HBL-100 and MCF-7 cells." (PMID 33748116, 2021).
hepatocellular carcinoma (5 papers, 2012 to 2023). A malignant tumor that arises from hepatocytes. "Silencing IFT88 resulted in the increased proliferation, migration, and invasion of hepatocellular carcinoma." (PMID 35454982, 2022).
retinal degeneration (5 papers, 2022 to 2025). Degeneration of the retina. "In mouse photoreceptors, a hypomorphic mutation in IFT88 exhibited retinal degeneration, and in humans, heterozygous mutations in IFT88 give rise to inherited retinal degeneration." (PMID 38373798, 2024). "A variety of genes involved in IFT, such as Ift88, Ift122, Ift81, Ift172, and Ift52, have been reported to be associated with retinal degeneration." (PMID 36171205, 2022). "In mouse photoreceptors, a hypomorphic mutation in the IFT88 gene exhibited abnormal OS development and retinal degeneration demonstrating that IFT88 is important for OS maintenance." (PMID 36074756, 2022). "Among 260 conserved genes between ift88−/− versus ift88+/+ and ift172−/− versus ift172+/+at 5 dpf (these mutants had the strongest retinal degeneration), we defined 65 retinal-associated differentially expressed genes (DEGs)." (PMID 36533556, 2022). "Interestingly, rhodopsin mislocalisation is reported in IFT88/Tg737 mutant mice and mutations in IFT88 have been found in individuals with non-syndromic recessive retinal degeneration." (PMID 39934925, 2025). "A major finding is that IFT88, IFT57 and IFT140 are depleted gradually after deletion of CEP164 at P16-P21, implicating IFT malfunction as the cause of retina degeneration in rodCep164-/- mice." (PMID 36074756, 2022).